LRG1 (leucine rich alpha-2-glycoprotein 1)
Diseases named in the same sentence as LRG1 in open-access papers (continued):
Sharing a sentence is not in itself a finding about the gene and the disease.
cancer (continued). "Although LRG1 has been implicated in cancer progression, the prognostic value in CRC and the relationship between LRG1 and microvessel destiny (MVD) remain unclear." (PMID 29029535, 2017). "Recently, studies revealed that LRG1 took part in multiple cancers progression and development." (PMID 29029535, 2017). "LRG1 was overexpressed in CRC tissues and associated with cancer aggressiveness." (PMID 26856989, 2016). "Although LRG1 is found to be implicated in various kinds of malignant carcinomas and benign diseases, the biological functions of LRG1 have not been fully elucidated." (PMID 26856989, 2016). "Intriguingly, the biomarker panel combined A1BG and LRG1 created by logistic regression had an AUC of 0.909 (0.851 to 0.968), higher than that of each protein, indicating the combination power of the two proteins to discriminate healthy and cancer sera." (PMID 23284758, 2012). "Moreover, it has been recently reported that CAFs themselves represent a source of LRG1 and that this can directly affect the invasive properties of CRC cells, thus placing LRG1 at the center of a mutual crosstalk between stromal and cancer cells in the metastatic TME." (PMID 35062948, 2022). "Moreover, recent evidence suggests that LRG1 might target cancer cells not only through the TGFβ signalling pathway but also by selective interaction with EGFR." (PMID 35062948, 2022). "Notably, data collected during a retrospective study revealed higher circulating levels of LRG1 in the plasma of subjects who were subsequently diagnosed with CRC, therefore suggesting that LRG1 might be also predictive of cancer onset." (PMID 35062948, 2022). "By manipulating LRG-1 expression, we may find a promising therapeutic treatment for HS and provide a new strategy for the treatment of diseases that involve biomechanical force and pathological angiogenesis, such as organ fibrosis and cancer." (PMID 31602408, 2019). "Furthermore, they also reported that LRG1 protein was highly expressed in cancer tissues." (PMID 28851367, 2017). "Therefore, LRG1 protein in urinary exosomes was derived from cancer tissues." (PMID 28851367, 2017). "The discrepancy of LRG1 function in certain kinds of cancers may be due to its tissue specificity." (PMID 26856989, 2016). "For mortality attributed to cancer, 28 proteins were statistically significant, with SERPINA3 showing the largest effect (2.79), alongside DDR1, LRG1, and GDF15 as the top contributors." (PMID 41270070, 2025). "Leucine-rich alpha-2-glycoprotein 1(LRG1), a well-known serum cancer biomarker, was shown to be substantially elevated in NSCLC EVs." (PMID 40026564, 2024). "LRG1 has been shown to bind to TGFβR2 and regulate various physiological processes involved in TGF-β signaling cascades in cancer and endothelial cells." (PMID 37569820, 2023). "LRG1 is a secreted protein belonging to the TGF-β superfamily that affects a plethora of normal and pathological processes involved in cancer and immunity (recently reviewed by Camilli and colleagues)." (PMID 36353660, 2022). "Targeting of LRG1 through this reported ADC presents a novel and effective proof-of-concept en route to improving the efficacy of cancer therapeutics." (PMID 34458833, 2021). "Interestingly, phosphorylation of Smad1/5 at Ser463/465, which has been implicated in epithelial-mesenchymal transition, was obviously induced in cancer cells by CAFs-derived CM, suggesting CAFs might be able to exert pro-metastatic role via LRG1-mediated activation of Smad1/5 signaling." (PMID 34930899, 2021). "Blockade of CAFs-LRG1 signaling cascade either by inhibitor or siRNA targeting JAK2/STAT3 axis can effectively attenuate migration and invasion of cancer cells induced by CAFs." (PMID 34930899, 2021). "LRG1 targeting through this ADC presents a novel and effective proof-of-concept en route to improving the efficacy of cancer therapeutics." (PMID 34458833, 2021).
cancer (continued). "Proteomic mass spectrometry showed that leucine rich alpha-2-glycoprotein 1 (LRG1) was highly expressed in urinary exosomes and also in cancer tissues from NSCLC patient in compare to healthy subjects." (PMID 29720982, 2018). "The final panel proteins (LRG1, TTR, and CA19-9) were tested on 1002 samples—composed of normal, benign, other cancers, and PDAC—which were divided into training (n=684) and test sets (n=318) at a 4:1 ratio." (PMID 29190982, 2017). "To investigate the mRNA expression level of LRG1 in CRC, we analysed the microarray data from two Oncomine Cancer Microarray databases (GSE20916 and GSE20842) and revealed remarkable overexpression of LRG1 in CRC tissues than normal tissues." (PMID 26856989, 2016). "Serum levels of LRG1 in patients with ccRCC (n = 64), non-ccRCC (n = 22), and without cancer (n = 63) were measured using ELISA." (PMID 38658967, 2024). "Using an enzyme-linked immunosorbent assay, serum levels of leucine-rich-alpha-2-glycoprotein 1 (LRG1) were measured in 64 patients with ccRCC and 22 patients non-ccRCC who underwent radical or partial nephrectomy, as well as in 63 patients without cancer." (PMID 38658967, 2024). "The median serum levels of LRG1, including the interquartile range, were 63.2 (42.8–94.2) μg/mL in ccRCC, 23.4 (17.7–29.6) μg/mL in non-ccRCC, and 36.0 (23.7–56.7) μg/mL in non-cancer patients, respectively." (PMID 38658967, 2024). "Furthermore, it is essential to validate the accuracy and sensitivity of LRG1 and APOA4 in larger sample cohorts, including those from patients with various types of cancer." (PMID 38735538, 2024). "Aside from endothelial cells, a major cell source of LRG1 in cancer is frequently the tumor cells but this is not always the case." (PMID 38745756, 2024). "Western blotting results demonstrated that the expression level of serum LRG1 in the patients with ccRCC was higher as compared to those with non-ccRCC or patients without cancer." (PMID 38658967, 2024). "The serum LRG1 level was significantly higher in patients with ccRCC than in those non-ccRCC (P < 0.001) or without cancer (P < 0.001)." (PMID 38658967, 2024). "LRG1 has also been evaluated in plasma alongside TTR and CA19-9, where this panel exceeded the accuracy of CA19-9 alone by over 10% in its ability to discriminate PDAC from benign controls and other cancers." (PMID 36969742, 2022). "As LRG1 has been shown to modify TGFβ non-canonical signalling in other pathological settings, it is not surprising that in cancer it can also exert its bioactivities through the p38/MAPK cascade." (PMID 35062948, 2022). "LRG1, another upregulated protein in NHL serum, was indicated to be involved in various cancers." (PMID 35371990, 2022). "Upregulation of LRG1 in cancer cells relied on JAK2/STAT3 signaling, we hypothesized that LRG1 could be a potential novel target regulated by STAT3." (PMID 34930899, 2021). "Although LRG1 was shown to participate in a variety of benign and malignant diseases, the molecular mechanism of LRG1 has not been fully clarified thus far." (PMID 28376129, 2017). "Two CCAs showed positive staining for LRG1, both in the malignant cells and non-neoplastic hepatocytes in the liver adjacent to the carcinomas, most marked in the periportal zones." (PMID 21970875, 2011). "The five proteins that met our criteria for an increase in relative abundance in the cancer compared to the control were haptoglobin (HAPT), orosomucoid-1 (ORM1), leucine-rich alpha-2-glycoprotein-1 (LRG1), alpha-1 antichymotrypsin (AACT), and fibrinogen-alpha (FGA)." (PMID 20546617, 2010). "Additionally, IL-22 upregulates expression of Erk1/2-independent genes such as Discoidin domain receptor tyrosine kinase 2 (DDR2), Lipocalin 2 (LCN2), and Leucine-rich alpha-2-glycoprotein 1 (LRG1), known for their involvement in the modulation of specific cancer hallmarks." (PMID 40806452, 2025).
cancer (continued). "However, the expression of LRG1 expression in the serum and cancer tissues of patients with RCC has not been reported." (PMID 38658967, 2024). "However, LRG1 expression in the serum and cancer tissues of patients with RCC has not been reported." (PMID 38658967, 2024). "Low LRG1 levels may reduce the number of T cells trained in lymph nodes to target cancer cells and thereby the antitumor immune activity." (PMID 36353660, 2022). "In this rare cancer, our discovery analysis of pooled serum samples using immunoaffinity depletion, 2D-DIGE and LC-MS/MS was able to detect differential protein expression between the BTC, benign and healthy groups, including upregulation of the putative marker LRG1." (PMID 21970875, 2011). "Median values of serum LRG1 and their inter-quartile ranges were 63.2 (42.8–94.2) μg/mL in ccRCC, 23.4 (17.7–29.6) μg/mL in non-ccRCC, and 36.0 (23.7–56.7) μg/mL in patients without cancer, respectively (ccRCC vs. non-ccRCC or patients without cancer: P < 0.001)." (PMID 38658967, 2024). "LRG1 targeting through the reported non-internalising ADC presents a novel and effective proof-of-concept en route to improving the efficacy of cancer therapeutics." (PMID 34458833, 2021).
tumor (78 papers, 2010 to 2026). "Hepatic LRG1 induced by tumor-associated inflammation via IL-6/STAT3 signaling promotes liver metastasis through the formation of TGFBR/PI3K/AKT axis-driven neutrophil extracellular traps (NETs)." (PMID 41963620, 2026). "Further, levels of LRG1 are associated with locally advanced disease and early tumor dissemination to the lymph nodes." (PMID 38386171, 2024). "In this context, we have shown that LRG1 is a causal factor in disrupting the endothelial-mural cell association in various tumour models and that antibody blockade or genetic deletion of Lrg1 results in improved mural cell coverage and vascular function." (PMID 35318338, 2022). "An important factor involved in pathogenic angiogenesis is leucine-rich α-2-glycoprotein 1 (LRG1), the antibody blockade of which has been shown to lead to a reduction in both choroidal neovascularization and tumor growth in mouse models." (PMID 35647920, 2022). "The percentage of Ki67+ cells in tumour tissues collected from Lrg1-deficient mice was comparable to that in wild-type controls." (PMID 34208965, 2021). "It is possible that Lrg1 derived from implanted B16F10 cells is able to compensate for the loss of Lrg1 in Lrg1-deficient mice, therefore, leaving tumour angiogenesis unaffected." (PMID 34208965, 2021). "Leucine-rich α2 glycoprotein (LRG1), a serum protein produced by hepatocytes, has been implicated in angiogenesis and tumor promotion." (PMID 28081565, 2017). "High LRG1 expression was significantly associated with tumor size (P = 0.004), tumor differentiation (P = 0.010), TNM stage (P < 0.001) and vascular invasion (P = 0.019)." (PMID 26517349, 2015). "In the validation cohort, high LRG1 expression was frequently associated with higher advanced clinical stage (P = 0.012), worse tumor differentiation (P = 0.035) and vascular invasion (P = 0.006)." (PMID 26517349, 2015). "Importantly, the concentrations of C9, CRP, and LRG1 are significantly associated with tumor size, reinforcing their potential role in GBM prognosis and clinical stratification." (PMID 40628732, 2025). "After observing an association between LRG1, leukocytes, and neutrophils, we next wanted to assess whether LRG1 is associated with proteins of known functions within anti-tumor immunity." (PMID 38386171, 2024). "Another tumor-promoting mechanism of LRG-1 is linked to tumor-related neoangiogenesis." (PMID 38413424, 2024). "Moreover, LRG1 has been associated with increased microvessel density, suggesting that it impacts tumor vascular growth." (PMID 38745756, 2024). "LRG1 is a newly identified regulator of pathogenic angiogenesis and tumor angiogenesis." (PMID 37786278, 2023). "Further, sEV-mediated transmission of UFC1 expression was upregulated in tumor serum sEVs from patients with NSCLC and high level of UFC1 were associated with tumor infiltration, while LRG1 is expressed at higher levels in urinary sEVs from patients with NSCLC." (PMID 34685415, 2021). "Although several studies implicated that LRG1 might be one of the chief culprits mediating tumor progression, the role of LRG1 in regulating metastasis remains largely unknown and seems to be controversial." (PMID 34930899, 2021). "Among these genes, LRG1 has attracted our attention since it ranked as the top hits and has recently been reported to be associated with tumor recurrence in CRC, though the underlying mechanism was unknown." (PMID 34930899, 2021). "Moreover, as larger tumours secrete more proteins into the circulation, LRG1 blood levels have been shown to positively correlate with tumour size further paving the way for LRG1 to stand as an accurate and tumour-related circulating biomarker with high diagnostic and prognostic value." (PMID 35062948, 2022). "Thus, fibroblasts in other fibrosis organs or tumor-associated fibroblasts under mechanical microenvironmental conditions may also be the main source of LRG-1 during these pathogenic processes." (PMID 31602408, 2019).
tumor (continued). "LRG1 remodels the tumor microenvironment by promoting proliferation, angiogenesis, and apoptotic sensitivity while repressing resistance-related genes." (PMID 42074251, 2026). "LRG1 has been shown to promote the formation of dysfunctional vessels in various disease conditions and to compromise pericyte coverage of tumour vessels." (PMID 40277918, 2025). "In accordance with these results, an increase in VE-cadherin expression and improved vascular function in B16F0 tumours following treatment with a LRG1-blocking antibody has been reported." (PMID 40277918, 2025). "Among the most promising biomarkers, the overexpression of complement component C9 (C9), C-reactive protein, and leucine-rich α-2-glycoprotein (LRG1) is strongly correlated with GBM tumor burden and progression." (PMID 40628732, 2025). "Advantages of exosomal LRG1 include its high specificity to MM, non-invasive detection through liquid biopsy, and potential for targeted therapies to disrupt its tumor-promoting effects, offering new strategies for MM diagnosis and treatment." (PMID 40303340, 2025). "The expression levels of PROS1 (P = .001), CLU (P < .001), and LRG1 (P = .002) were significantly lower in PTC patients with large tumor size (>2 cm) than in small tumor size patients (≤2 cm), respectively." (PMID 40797389, 2025). "In this study, we assessed serum levels of LRG-1 in patients with early BC and investigated its correlation with the presence of disseminated tumor cells (DTCs) in the bone marrow and survival outcomes." (PMID 38413424, 2024). "Consistent with LRG1 playing a role in tumor progression, LRG1 blockade in different tumor models inhibits growth and improves survival and thus has been proposed as a potentially beneficial therapeutic target." (PMID 38745756, 2024). "Nevertheless, this was sufficient to impact on tumor growth as Lrg1 knock-out or antibody blockade were still effective in reducing tumor growth." (PMID 38745756, 2024). "Here, LRG-1 from different cellular sources promotes pathological vessel formation, immunosuppression, epithelial-to-mesenchymal transition, metastasis and tumor cell proliferation." (PMID 38413424, 2024). "As a likely consequence of vascular normalization, LRG1 inhibition not only led to significant improvements in the delivery and efficacy of anti-tumor therapies, but also improved immune-cell infiltration." (PMID 38745756, 2024). "This suggests that Lrg1 is one of the few genes to be expressed in both tumor angiogenic and co-opted endothelial cells." (PMID 38745756, 2024). "In this context, Lrg1 gene deletion, or functional blockade of the protein, has been shown to improve tumor vascular function as manifested by better perfusion, reduced tumor hypoxia and reduced vascular leakage." (PMID 38745756, 2024). "Through a different mechanism, liver endothelium-derived LRG1 has been shown to promote tumor growth and metastasis of colorectal cancer in a paracrine manner through binding to the HER3 receptor, leading to its phosphorylation and activation." (PMID 38745756, 2024). "Our data show that the HPV status of the tumor correlates with the expression level of LRG1 in OPSCC." (PMID 38898137, 2024). "LRG-1 plays a role in inflammation, fibrosis, metabolism, and angiogenesis, all of which contribute to tumor initiation and progression." (PMID 38413424, 2024). "Although LRG1 levels appeared unaffected throughout the treatment protocol, patients with high LRG1 also expressed other proteins that would serve a purpose in the local clearing of the tumor and incite long-term anti-tumor memory." (PMID 38386171, 2024). "LRG1 was significantly elevated in the in situ tumor transcriptome data, consistent with the findings in plasma." (PMID 38735538, 2024). "In particular, LRG1 acts directly on tumor cell proliferation, migration, and invasion contributing to tumor growth and survival, and these functions have been described in detail elsewhere." (PMID 38745756, 2024).